SYT1 (synaptotagmin 1)
Description:
Calcium sensor that participates in triggering neurotransmitter release at the synapse (By similarity). May have a regulatory role in the membrane interactions during trafficking of synaptic vesicles at the active zone of the synapse (By similarity). It binds acidic phospholipids with a specificity that requires the presence of both an acidic head group and a diacyl backbone. A Ca(2+)- dependent interaction between synaptotagmin and putative receptors for activated protein kinase C has also been reported. It can bind to at least three additional proteins in a Ca(2+)-independent manner; these are neurexins, syntaxin and AP2. Plays a role in dendrite formation by melanocytes.
Synonyms: SVP65; SYT; P65; BAGOS
Tractability: Small molecule: it has a high-quality binding pocket. Antibody: its Gene Ontology location is reachable by antibodies, with high confidence; UniProt predicts a signal peptide or a membrane-spanning region. PROTAC: ubiquitination databases record sites on it; its protein half-life has been measured.
Safety:
Unwanted effects reported when the protein is acted on. In parentheses: how it was acted on, where the effect was seen, and who reports it.
cocaine dependence (source: ClinPGx)
Gene: Protein-coding gene on chromosome 12 (78,863,650 to 79,452,009, forward strand). Ensembl gene ENSG00000067715.
Subcellular location: Cytoplasmic vesicle, secretory vesicle membrane; Cytoplasmic vesicle, secretory vesicle, synaptic vesicle membrane; Cytoplasmic vesicle, secretory vesicle, chromaffin granule membrane; Cytoplasm
Pathways (Reactome):
Neuronal System: Acetylcholine Neurotransmitter Release Cycle; Dopamine Neurotransmitter Release Cycle; GABA synthesis, release, reuptake and degradation; Glutamate Neurotransmitter Release Cycle; Neurexins and neuroligins; Norepinephrine Neurotransmitter Release Cycle; Serotonin Neurotransmitter Release Cycle
Disease: Toxicity of botulinum toxin type B (botB); Toxicity of botulinum toxin type G (botG)
Vesicle-mediated transport: Cargo recognition for clathrin-mediated endocytosis; Clathrin-mediated endocytosis
Gene Ontology:
Molecular function: lipid binding; low-density lipoprotein particle receptor binding; phospholipid binding; protein binding; calcium ion sensor activity; calcium-dependent phospholipid binding; SNARE binding; syntaxin-1 binding; calcium ion binding; calcium-dependent protein binding; calmodulin binding; clathrin binding; identical protein binding; molecular condensate scaffold activity; phosphatidylinositol-4,5-bisphosphate binding; phosphatidylserine binding; protein heterodimerization activity
Biological process: positive regulation of dendrite extension; vesicle organization; calcium-dependent activation of synaptic vesicle fusion; cellular response to calcium ion; chemical synaptic transmission; detection of calcium ion; fast, calcium ion-dependent exocytosis of neurotransmitter; neurotransmitter secretion; positive regulation of calcium ion-dependent exocytosis of neurotransmitter; positive regulation of synaptic transmission; regulation of calcium ion-dependent exocytosis; regulation of exocytosis; regulation of regulated secretory pathway; regulation of synaptic transmission, glutamatergic; regulation of synaptic vesicle exocytosis; vesicle-mediated transport; calcium activated phospholipid scrambling; inhibitory postsynaptic potential; membraneless organelle assembly; negative regulation of neurotransmitter secretion; positive regulation of calcium ion-dependent exocytosis; positive regulation of dopamine secretion; positive regulation of vesicle fusion; protein complex oligomerization; protein heterooligomerization; and 10 more
Cellular component: cytoplasm; presynaptic membrane; axon; clathrin-coated endocytic vesicle membrane; clathrin-sculpted acetylcholine transport vesicle membrane; clathrin-sculpted gamma-aminobutyric acid transport vesicle membrane; clathrin-sculpted glutamate transport vesicle membrane; clathrin-sculpted monoamine transport vesicle membrane; dense core granule; exocytic vesicle; neuron projection; plasma membrane; synaptic vesicle; synaptic vesicle membrane; chromaffin granule membrane; excitatory synapse; glutamatergic synapse; Golgi apparatus; hippocampal mossy fiber to CA3 synapse; membrane; neuron projection terminus; postsynaptic cytosol; postsynaptic density; postsynaptic membrane; presynaptic active zone; and 5 more
Genetic constraint (gnomAD): Loss-of-function variants: 8 observed, 43.52 expected, observed/expected ratio (o/e) 0.18, 90% interval 0.11 to 0.33. The upper end of that interval is the gene's LOEUF score, 0.33, which puts it in group 1 of 6, group 1 being the genes least tolerant of losing a copy. Missense variants: 248 observed, 491.35 expected, observed/expected ratio (o/e) 0.5, 90% interval 0.45 to 0.56. Synonymous variants: 142 observed, 181.01 expected, observed/expected ratio (o/e) 0.78, 90% interval 0.68 to 0.9.
Homologues: Orthologues: chimpanzee SYT1 (100% identical), macaque SYT1 (100% identical), dog SYT1 (99% identical), guinea pig SYT1 (99% identical), rabbit SYT1 (99% identical), rat Syt1 (98% identical), mouse Syt1 (98% identical), tropical clawed frog syt1 (90% identical), pig SYT1 (89% identical), zebrafish syt1a (82% identical), zebrafish syt1b (60% identical). Paralogues in human: SYT2 (76% identical), SYT5 (55% identical), SYT10 (39% identical), SYT3 (38% identical), SYT6 (38% identical), SYT8 (36% identical), SYT9 (36% identical), SYT7 (35% identical), SYT11 (32% identical), SYT17 (31% identical), SYT4 (31% identical), RPH3A (28% identical), and 19 more.
Diseases named in the same sentence as SYT1 in open-access papers:
SYT1 is named in the same sentence as 90 diseases in open-access papers, as found by Europe PMC text mining. Sharing a sentence is not in itself a finding about the gene and the disease. The quoted sentences say what the papers report.
Alzheimer disease (19 papers, 2008 to 2026). A progressive, neurodegenerative disease characterized by loss of function and death of nerve cells in several areas of the brain leading to loss of cognitive function such as memory and language. "It is reported that SYT1 expression is reduced in Alzheimer’s disease brains as a result of synaptic loss." (PMID 36518382, 2022). "It was also observed that CSF synaptotagmin-1 levels in patients with dementia due to Alzheimer’s disease were significantly lower compared to those with mild cognitive impairment due to Alzheimer’s disease." (PMID 33578866, 2021). "Herein, we found that synaptotagmin-1 correlated with the levels of total tau and phosphorylated tau both in the control group and in patients with dementia due to Alzheimer’s disease in both investigated sample sets." (PMID 27716408, 2016). "In sample set I, the tryptic peptides of synaptotagmin-1 were significantly higher in patients with MCI due to Alzheimer’s disease compared with patients with dementia due to Alzheimer’s disease." (PMID 27716408, 2016). "We found that the CSF levels of synaptotagmin-1 were consistently elevated in patients with dementia due to Alzheimer’s disease compared with controls in two separate sample sets." (PMID 27716408, 2016). "The aim of the study was to investigate the potential of synaptotagmin-1 as a CSF biomarker in dementia due to Alzheimer’s disease and in MCI due to Alzheimer’s disease." (PMID 27716408, 2016). "In both investigated sample sets, the CSF levels of synaptotagmin-1 were significantly increased in patients with dementia due to Alzheimer’s disease (P ≤ 0.0001) and in patients with mild cognitive impairment due to Alzheimer’s disease (P < 0.001)." (PMID 27716408, 2016). "In patients affected with Alzheimer's disease, a downregulation of Syt1 was observed in different brain regions." (PMID 23236410, 2012). "Synaptotagmin-1 is keenly involved in the release of neurotransmitters through its interactions with the SNARE complex and phospholipid membranes, and it has previously been reported to be increased in Alzheimer’s disease–associated pathologies." (PMID 34618331, 2022). "Interestingly, in a recent study, CSF synaptotagmin-1 levels were higher in Alzheimer’s disease patients compared to those with frontotemporal dementia, and there was a tendency to increased levels in patients with likely tau pathology." (PMID 33578866, 2021). "Because synaptic degeneration is a prominent feature in the brain in Alzheimer’s disease, we expected synaptotagmin-1 to be altered in these patients compared with controls and therefore it might serve as a valuable biomarker for Alzheimer’s disease." (PMID 27716408, 2016). "To summarize, our results suggest that synaptotagmin-1 might be a specific marker for dementia due to Alzheimer’s disease that to some extent also might reflect general neurodegeneration." (PMID 27716408, 2016). "Furthermore, synaptotagmin-1 was even higher in MCI due to Alzheimer’s disease compared with dementia due to Alzheimer’s disease, suggesting that synaptic dysfunction and degeneration can be identified before the onset of clinical dementia." (PMID 27716408, 2016). "Each measured tryptic peptide of synaptotagmin-1 (215–223 and 238–245) could differentiate dementia due to Alzheimer’s disease from controls and MCI due to Alzheimer’s disease from controls to a similar magnitude, in the respective sample sets." (PMID 27716408, 2016). "In addition, in sample set I the synaptotagmin-1 level was significantly higher in patients with mild cognitive impairment due to Alzheimer’s disease compared with patients with dementia due to Alzheimer’s disease (P ≤ 0.05)." (PMID 27716408, 2016). "Indeed, several studies have found a marked reduction of synaptotagmin-1 in typical disease-affected cortical brain regions in Alzheimer’s disease and a colocalization of synaptotagmin-1 with neuritic plaques." (PMID 27716408, 2016).
Alzheimer disease (continued). "Additionally, synaptotagmin-1 was increased already in MCI due to Alzheimer’s disease, supporting the notion that this synaptic marker might be an early marker for Alzheimer’s disease." (PMID 27716408, 2016). "It is important to recognize that menin’s association with synaptic proteins such as SYT-1 and PSD-95 is essential not only for the development of synapses but also their maintenance; the perturbation of these proteins may likely underlie neurodegenerative diseases such as Alzheimer’s disease." (PMID 34065662, 2021). "In this study, we investigated the potential of synaptotagmin-1 as a CSF biomarker in dementia due to Alzheimer’s disease and in MCI due to Alzheimer’s disease." (PMID 27716408, 2016). "The tryptic peptides of synaptotagmin-1 assays also correlated with each other in all investigated groups (controls, MCI due to Alzheimer’s disease, and dementia due to Alzheimer’s disease) in the respective sample sets." (PMID 27716408, 2016). "The CSF levels of the investigated tryptic peptides of synaptotagmin-1 were significantly higher in patients with MCI due to Alzheimer’s disease and patients with dementia due to Alzheimer’s disease compared with controls." (PMID 27716408, 2016). "Among the genes being down-regulated in the brains of Eya3 mutants, several are reported to be down-regulated also in Alzheimer's disease, e.g. ARPP19, BIRC4, MT3, SYT1 or TTR." (PMID 19102749, 2008). "Intriguingly, there is a specific reduction in synaptophysin levels at the earliest stages of Alzheimer’s disease with no change in the levels of other presynaptic proteins such as synaptotagmin-1 or GAP-43." (PMID 26871701, 2016). "Moreover, we show that both Syt-1 and Syt-9 increase Aβ levels likely via BACE1-mediated APP processing and thus may play an important role in Alzheimer’s disease pathology." (PMID 26202512, 2015). "Many of the SNARE complex genes involved in presynaptic vesicle exocytosis were significantly downregulated in Alzheimer’s disease, including SNAP-25, STX1A, SYT1 and VAMP2, while STX2, SYN1 and VAMP3 were not changed." (PMID 34423299, 2021).
Cognitive impairment (15 papers, 2016 to 2024). Abnormal cognition is characterized by deficits in thinking, reasoning, or remembering. "Surprisingly, our results showed that MSD-induced cognitive impairment was associated with increased Syt-1 expression." (PMID 35910680, 2022). "The results are in accordance with a previous report that upregulation of Syt-1 in the hippocampus has been found to cause neuron damage associated with prenatal stress- and hypothyroidism-induced cognitive impairment." (PMID 35910680, 2022). "Brain-derived neurotrophic factor (BDNF) and Synaptotagmin-1 (Syt-1) are two important synaptic plasticity markers, which have been experimentally confirmed to be associated with cognitive impairment induced by early life stress." (PMID 35910680, 2022). "The observed cognitive impairment could be associated with the expression of altered hippocampal of Bdnf and Syt-1 genes." (PMID 36570704, 2022). "Our findings indicated that prenatal exposure to inflammation or stress exposure in adolescence exacerbated the AISLM and age-related upregulation of Arc and Syt1 expression, and these effects were linked to cognitive impairments in CD-1 mice exposed to adverse factors in early life." (PMID 32774299, 2020). "Moreover, EE could improve MSD associated-cognitive deficits by reducing Syt-1 expression, which was consistent with our previous study that exposure to an EE from adolescence improved age-associated cognitive decline by downregulating the expression of Syt-1." (PMID 35910680, 2022). "The reduction or loss of SNAP-25, SY1A, SYT1, and SYN expressions causes memory impairment and cognitive deficit in AD." (PMID 36873105, 2023). "Our findings are consistent with prior studies showing higher SNAP-25, synaptotagmin-1, GAP-43, and neurogranin levels in CSF are associated with cognitive impairment in AD, which may be linked to synapse degeneration in the brain." (PMID 38299587, 2024). "The contradictory results regarding the relationship between Syt-1 expression level and cognitive function could be a result of differences in the specific mechanisms leading to cognitive impairment in different pathological models." (PMID 35910680, 2022). "A recent Chinese study revealed that exosomal SNAP25, GAP43, neurogranin, and synaptotagmin-1, combined with APOE ε4 status, improved diagnostic accuracy (AUC = 0.88), acting as a useful biomarkers panel for the prediction of AD five to seven years before cognitive impairment." (PMID 35360215, 2022). "The cognitive impairment induced by MSD was associated with a decreased brain-derived neurotrophic factor and an increased Synaptotagmin-1, while EE increased and decreased brain-derived neurotrophic factor and Synaptotagmin-1 in the hippocampus of mice from the MSD+EE group, respectively." (PMID 35910680, 2022). "This reduction of SNAP-25, SY1A, SYT1, and SYN leads to cognitive impairment and memory dysfunction, which can be reversed by an increase in SNAP-25, SY1A, SYT1, and SYN following the blockage of presynaptic N-type VGCCs with omega-agatoxin-Aa2a." (PMID 36873105, 2023). "Our study demonstrated that MSD-induced offspring exhibited anxiety-like behavior, cognitive impairment, and BDNF and Syt-1 expression." (PMID 35910680, 2022).
epilepsy (10 papers, 2017 to 2026). A brain disorder characterized by episodes of abnormally increased neuronal discharge resulting in transient episodes of sensory or motor neurological dysfunction, or psychic dysfunction. "Further evidence of a potential link between SV2A loss of function, dysregulated Syt1 trafficking and epilepsy comes from the only human SV2A missense mutation to be investigated in detail (R383Q)." (PMID 39853744, 2025). "Mutations in the plasma membrane SNARE protein SNAP-25 result in epilepsy and intellectual disability; these mutations occur in or near residues that bind directly to the C2B domain of SYT1." (PMID 30107533, 2018). "Additional cases are required to clarify the association between SYT1 and epilepsy risk." (PMID 35101335, 2022). "There were 771 out of 5648 DEGs that were successfully converted into human orthologs and significantly enriched in neuropsychiatric disorders (e.g., epilepsy and anxiety), including synaptic vesicle glycoprotein 2A (sv2a) and synapse proteins (e.g., syt1)." (PMID 39083243, 2025). "The potential for SV2A‐dependent epilepsy to be a result of dysfunctional Syt1 expression and localisation is also discussed." (PMID 39853744, 2025). "Disruption of SV2A leads to Syt1 mislocalization and impaired neurotransmission, a mechanism that may contribute to epilepsy." (PMID 40430045, 2025). "Intriguingly, there are potential links between SV2A dysfunction, epilepsy and Syt1." (PMID 39853744, 2025). "How could altered Syt1 expression/trafficking potentially result in epilepsy?" (PMID 39853744, 2025).
Baker-Gordon syndrome (8 papers, 2020 to 2025). "Baker–Gordon syndrome (BAGOS) is an autosomal dominant neurodevelopmental disorder caused by de novo heterozygous missense mutations in SYT1." (PMID 41438914, 2025). "Variants in the SYT1 gene, which codes for the protein synaptotagmin-1 (SYT1), give rise to SYT1-associated neurodevelopmental disorder, also known as Baker-Gordon Syndrome (OMIM 618218)." (PMID 35101335, 2022). "SYT1 mutations in Baker–Gordon syndrome cause infantile hypotonia, ophthalamic abnormalities, hyperkinetic movement disorders, motor stereotypies, and DD57." (PMID 32929080, 2020). "SYT1, which functions as calcium sensors in vesicular trafficking and exocytosis of neurotransmitters and hormones, is involved in the regulation of neurite outgrowth and it is linked to a rare neurodevelopmental disorder known as SYT1-associated neurodevelopmental disorder or Baker-Gordon syndrome." (PMID 36674445, 2023).
depression (8 papers, 2015 to 2024). "Early-life stress increases susceptibility to depression in adolescent mice by regulating the miR-34c-5p/synaptotagmin-1 (SYT1) axis and disrupting hippocampal neuroplasticity." (PMID 39253375, 2024).